SMAD7 (SMAD family member 7)
Diseases named in the same sentence as SMAD7 in open-access papers (continued):
Sharing a sentence is not in itself a finding about the gene and the disease.
tumor (continued). "Accordingly, SMAD7 might exhibit both tumor-suppressive or tumor-promotive effects, depending on spatial–temporal regulation of its biological action." (PMID 28134936, 2017). "SMAD7 KO mice presented with increased pSMAD2/3 levels and decreased apoptosis in the tumor tissue." (PMID 28134936, 2017). "We next correlated Smad7 mRNA levels detected by RT–PCR in tumors or surrounding tissue of mouse livers with tumor numbers in the respective animals, regardless of the underlying mouse genotype or the expression ratio of Smad7 in tumors vs surrounding tissue." (PMID 28134936, 2017). "Smad7 was up-regulated in HCC tissues compared with adjacent non-tumor tissues." (PMID 26759305, 2016). "In vivo and in vitro studies also support the important role of SMAD7 in tumor progression of HCC." (PMID 26989026, 2016). "Smad7 is frequently elevated in various tumor types including squamous cancers of the skin." (PMID 27536941, 2016). "Interestingly, recent reports indicated that several miRNAs induced tumor metastasis through targeting Smad7." (PMID 27006642, 2016). "EMT is a process that exerts influence on many molecular, such as TGF-β, E-cadherin, N-cadherin Vimentin, ZEB-1, SMAD-2, SMAD-3, SMAD-7, GLI1 and GLI2; these molecules are closely associated with typical phenotype changes of EMT in tumor cell growth and metastasis." (PMID 25895132, 2015). "However, overexpression of miR-216a was shown to activate the PI3K/Akt and TGF-β pathways by targeting PTEN and SMAD7, contributing to hepatocarcinogenesis and tumor recurrence in heptaocellular carcinoma." (PMID 25807141, 2015). "Smad7’s anti-inflammatory effect in certain tissues and induction of apoptosis in certain cancer types could contribute to its tumor-suppressive effect." (PMID 25566830, 2015). "STAT pathway and NF-κB pathway also induce Smad7, thus, tumor cells with high activity of those pathways might evade the TGF-β cytostatic responses through overexpression of Smad7." (PMID 24891760, 2014). "As SMAD7 has a crucial regulatory role in the TGF-b signaling pathway which strongly contributed to tumor initiation and development, the present study was organized to investigate the correlation between one polymorphism of SMAD7 gene, rs2337104, and CRC risk in an Iranian population." (PMID 25289133, 2014). "It is known that the increased expression of TGF-β, Vimentin, ZEB-1and N-cadherin could promote EMT progression of tumor cells, whereas the decreased expression of SMAD-7 and E-cadherin could inhibit the EMT progression." (PMID 24625224, 2014). "There was some indication of differences in the effect of SMAD7 SNPs by tumor location." (PMID 23560096, 2013). "Stable over-expression of Smad7 in 1205Lu cells reduced production of tissue-degrading proteases and hence the invasive capacity and the in vitro anchorage-independent growth as well as tumor formation following subcutaneous injection in nude mice." (PMID 24317436, 2013). "Moreover, tumor cells from Smad7 KO mice displayed increased proliferation, diminished apoptosis and higher colony formation compared with those from wild-type littermates." (PMID 24317436, 2013). "In addition to confirming the associations between SMAD7 SNPs and CRC risk, we further defined these associations according to other known risk/protective factors for CRC and tumor characteristics." (PMID 23560096, 2013). "In addition, TGF-β1 was highly expressed in the higher metastatic group and the expression of Smad7 negatively correlated with tumor size." (PMID 23251254, 2013). "Moreover, even in the same tumor the function of Smad7 can switch from tumor-suppressive to tumor-promoting depending on the tumor stage (i.e., early versus advanced)." (PMID 24317436, 2013). "Moreover, Smad7 mRNA levels were linearly and negatively correlated with tumor weight (R2=0.18, P=0.005)." (PMID 23251254, 2013). "Interestingly, Smad7 has also been reported to inhibit tumor formation and metastasis as revealed by various studies." (PMID 22204639, 2011).
tumor (continued). "In addition SMAD7 was found to be higher expressed in VEGFA165 tumours compared with control tumours." (PMID 22045186, 2011). "The FET cells have an activating mutation in K-Ras, and activation of MAPK/ERK and AKT pathways in the liver metastases coupled with the suppression of growth inhibitory effects of TGF-β by Smad7 may exert a selective pressure for tumour outgrowth." (PMID 18781153, 2008). "On the other hand, some upregulated genes, such as STAT1 and SMAD7, could have pro-tumor effects." (PMID 37834191, 2023). "In addition, SMAD7 ctDNA methylation levels were significantly reduced in patients after LAD tumors were resected as compared with those in the same group of patients before tumor resection (n = 14)." (PMID 37072414, 2023). "Considering that SMAD7 acts as a transcriptional regulator and ZNF281 is a tumor-suppressive long non-coding (lnc)RNA, an increase in hsa-miR-33a-5p could lead to the downregulation of these factors and consequently to a loss of tumor suppression capability." (PMID 36979715, 2023). "In line with in vitro study, the expression of E-cadherin and Smad7 was dramatically increased and that of Ki-67, N-cadherin and Vimentin was significantly decreased in the xenograft tumor with overexpression of circFGGY, which could be rescued by miR-545-3p agomir." (PMID 35592246, 2022). "Additionally, a previous study suggested that the overexpression of SMAD7 may suppress tumour progression by antagonizing TGF-β, while the high expression and low methylation of SMAD7 in our EIC were associated with poor prognosis for LUSC." (PMID 35799269, 2022). "Thus, in general, the type of tumor cell seems to determine whether Smad7 acts as a promoter or suppressor." (PMID 34059951, 2021). "Since, in IBD mucosa, Smad7 is over-expressed in effector T cells and positively regulates production of T cell-derived cytokines/molecules, which could potentially influence tumor cell growth and survival, we investigated the role of Smad7-expressing immune cells in the control of CAC development." (PMID 31052449, 2019). "Smad7 overexpression decreased the number and total weight of disseminated nodes compared with those in the negative control, while Smad7 knockdown increased them, attenuating the miR-520h overexpression or knockdown-induced promotion or inhibition of tumour dissemination, respectively." (PMID 30158641, 2018). "Besides negatively regulating TGF-β signaling, tumor-suppressive functions might be due to crosstalks of SMAD7 with other signaling pathways, such as JNK, NF-κB and STAT3." (PMID 28134936, 2017). "SMAD7 might represent a target for inhibition of IL-1α induced tumor stroma interactions." (PMID 27473228, 2016). "Furthermore, miR-182 expression inversely correlates with SMAD7 protein in human tumour samples." (PMID 27996004, 2016). "For instance, while high levels of Smad7 overexpression driven by adenoviral transduction cause skin tumor progression in immune compromised recipient mice, we have not observed spontaneous tumor formation in K5." (PMID 25566830, 2015). "However, since Smad7 overexpression only occurred in fibroblasts directly co-cultured with tumour cells, this suggests that cell surface factors may be involved in regulation of Smad7." (PMID 24090133, 2013). "Altogether, these observations suggest that Smad7 may act as a tumor suppressor in HCC." (PMID 24317436, 2013). "Tumour cells may be communicating with fibroblasts in a paracrine manner by secreting soluble factors such as cytokines and growth factors that can modulate Smad7, CCN2 and type I collagen gene expression in neighbouring fibroblasts via such secreted factors." (PMID 24090133, 2013). "Eventually, the binding of Smad7 in the presence of ProT resulted in reduced expression of the EMT transcription factors, leading to the inhibition of TGF‐β‐induced EMT and tumor metastasis." (PMID 40259641, 2025).
tumor (continued). "Dysregulation of inhibitory Smads (e.g., Smad7) further enhances TGF-β-driven fibrosis and tumor-stromal interactions, accelerating disease progression." (PMID 41301482, 2025). "As the marker of exhaustive CD8 T cells, HAVCR2 regulates EMT by crosstalking Akt/GSK-3β/Snail signaling pathway with SMAD7/SMAD2/ SNAIL1 Axis, implicating the dual role of Community 1-related immune genes in EMT and tumor immune." (PMID 38331768, 2024). "Overexpression of SMAD7 reduces primary tumor growth by blocking TGF-β activity in OS to affect the relationship between tumor and non-tumor cells." (PMID 37206921, 2023). "The target genes of miR-21 include PDCD4, SMAD7, PTEN, HIF-1α, KRIT1, and other tumor suppressor genes." (PMID 37316504, 2023). "MiR-216a positively regulated TGF-β and the canonical pathway implicated in the promotion of the PI3K/Akt cascade in HCC cells by inhibiting SMAD7 and PTEN, resulting in tumor relapse and sorafenib resistance." (PMID 36740668, 2023). "In a subgroup analysis based on tumour node metastasis (TNM) stage, SMAD4 and SMAD7 showed the most significant prognostic differences in patients with stage I gastric cancer." (PMID 37685308, 2023). "Relatively, OTUD1 also can inhibit tumor metastasis by preventing the degradation of SMAD family member 7 (SMDA7), which can inhibit tumor metastasis by blocking TGF-β signaling pathway." (PMID 37251574, 2023). "Previous studies have revealed that SNAI3-AS1 is upregulated in HCC, and can promote tumor cell proliferation and metastasis by activating UPF1/Smad7 signaling pathway and by acting as a sponge for miR-27-3p and miR-34a-5p to upregulate PEG10." (PMID 37202791, 2023). "Tumor cells undergoing autophagy upregulate E3 ubiquitin ligase and promote the degradation of SMAD7, thus activating TGFβ/SMAD signaling, inducing EMT, and promoting tumor cell proliferation and migration, which produces resistance to chemotherapeutics." (PMID 35684449, 2022). "qRT-PCR and Western blot results exhibited abundant expression of miR-642b-3p and Smad7 yet poor expression of CSMD1 and Smad4 in the tumor tissue of mice treated with miR-642b-3p mimic, the effects of which were undermined by CSMD1." (PMID 35412956, 2022). "Moreover, Jab1/CSN5 can induce the degradation of two important downstream molecules, Smad4 and Smad7, and affect transforming growth factor-b (TGFb) signaling which is also influenced by various factors in the tumor microenvironment, and might contribute to lymphatic and distant metastasis." (PMID 35870903, 2022). "Through regulation of different pathways (CADM1, SOCS2, Smad7, OTX1), miR-424-5p can act to inhibit tumor progression." (PMID 35409396, 2022). "RNA-sequencing data from the Tumor, Normal and Metastatic (TNM) plot database showed a positive correlation between Smad7 and Stat3 in 1450 CRC samples." (PMID 36291778, 2022). "Sunitinib inhibits tumor progression by inhibiting p-VEGFR-PI3K-AKT-YBX1-Snail, SMAD4/SMAD7, ERK1/2 and MAPK signaling pathways." (PMID 36544713, 2022). "Tumours containing AdSDC2‐transduced TASCs had elevated RNA levels of SDC2, SMAD7 and PAI‐1 (P < .05)." (PMID 33152121, 2021). "High expression of Smad7 and low expression of TGFβR1 in HCC tumors and surrounding normal liver tissues can be tumor suppressive." (PMID 34323416, 2021). "CERS4 (ceramide synthase 4) generates ceramide, which binds to Smad7 and limits the aggregation of TGF-β receptor in the primary cilia, thereby blocking tumor cell migration." (PMID 33996533, 2021). "Some studies have pointed out that overexpression of miR-106b in breast cancer can inhibit the expression of Smad7, further enhance TGF-β signal pathway, lead to the occurrence of EMT and promote tumor progression." (PMID 34775378, 2021). "Next, we evaluated the specific promoter methylation of the four genes from the TGFβ signaling pathway (TGFBR2, SMAD4, SMAD7 and SNAI1) evaluated in SNU449 cells in resected human HCC tumors, as well as in the surrounding non-tumor tissues." (PMID 34571856, 2021).
tumor (continued). "A1BG-AS1 also acted as a tumor suppressor lncRNA and potentiated the expression of PTEN and SMAD7 in HepG2 cells." (PMID 33511320, 2021). "SMAD7 and SKIL are well known as negative regulators of TGF-β signaling, and KLF10 is believed to play a crucial role as a tumor suppressor with unique tissue-specific functions mediated by TGF-β signaling." (PMID 32629802, 2020). "Interestingly, tumors of Smad7 transgenic mice showed higher levels of IFN-γ as compared to wild-type mice, while the other cytokines analyzed were downregulated, indicating a prevalent IFN-γ-associated immune response within the tumor environment of transgenic mice." (PMID 31052449, 2019). "Surprisingly, we found that the TGF-β component SMAD7 was up-regulated in the Tan IIA group, which was consistent with the anti-tumor effect noted in our PCR array results." (PMID 31711043, 2019). "Here we shown a down-regulation of Smad7 in treated cells, supporting the idea that PRP treatment promotes a deep change in TGFβ pathway and decreases tumour malignancy." (PMID 31388092, 2019). "miR-106b is reported to promote the tumor growth through targeting tumor suppressor genes, such as Pten, Cdkn1a, E2F1, Setd2, Runx3, Smad7, Cdkn1a, and Bim." (PMID 31547867, 2019). "There is evidence that the pro-tumorigenic effects of Smad7 in CRC are, at least in part, dependent on the inhibition of the tumor-suppressive properties of TGF-β1 in the normal epithelium." (PMID 31052449, 2019). "Functional analyses of miR-324-3p on tumour were just seen in our preceding study and another similar report of NPC radioresistance, in which SMAD7 was validated as the target of miR-324-3p." (PMID 28053597, 2017). "There are other reported targets for miR-106b, such as PTEN, SMAD7 and REST and downregulation of these targets by miR-106b also contributes to tumor progression." (PMID 28422740, 2017). "On the one hand, SMAD7 can interfere with TGF-β signaling and therefore can change its roles in the process of tumor development." (PMID 28134936, 2017). "Our results described that miR-424-5p -SMAD7 pathway contributed to ESCC invasion and metastasis and up-regulation of miR-424-5p perhaps provided a strategy for preventing tumor invasion, metastasis." (PMID 27628042, 2016). "RHOA, SMAD2, SMAD4, SMAD5, SMAD6, BMPR1A, SMAD7 and MYC-, which thereby emerge as candidate genes to play an important role in CRC tumor metastasis." (PMID 27662660, 2016). "MiR-802 is the third most significantly repressed miRNA in PDAC, besides the tumor suppressor miRNAs miR-216 and miR-217 that - among others - target KRAS, PTEN, and SMAD7." (PMID 25910082, 2015). "In our study, tumours overexpressing VEGFA165 showed lower expression of TGFBR2 and higher expression of SMAD7, suggesting a resistance to the TGF-β-induced cell cycle arrest." (PMID 22045186, 2011). "Gene expression profiling revealed human genes involved in TGF-β signalling differentially expressed between both tumour groups, that is, TGFBR2 and SMAD5 were lower expressed whereas the inhibitory SMAD7 was higher expressed with VEGFA165." (PMID 22045186, 2011). "The activation of TGF-β signalling led to increased downstream gene expression, as indicated by the correlation of SMAD7 expression—a typical SMAD-positively regulated gene—with TGFB1 in human iCCA and the increased Smad7 mRNA expression in tumours from the mouse iCCA models." (PMID 40820091, 2025). "They concluded that SMAD7 could act as a prognostic indicator in CRC patients and plays a significant role in tumor suppression." (PMID 38275467, 2024). "At day 9 post-tumour implantation, mice were intracranially treated with either control adenovirus (Ad-CMV-Tom) or adenoviruses targeting TGF-β signaling activity (Ad-Smad6 or Ad-Smad7)." (PMID 39724753, 2024).
tumor (continued). "In addition, miR-21 is also implicated in the development of chemotherapy resistance, as it is either directly involved in the regulation of tumor suppressor genes such as PTEN, PDCD4, and SMAD7 or indirectly involved in apoptosis inhibition." (PMID 38542098, 2024). "Besides, we investigated the expression of SMAD7 in CRC using GEPIA, which indicated that SAMD7 expression was lower in tumor tissues compared to normal tissues in COAD, as well as READ." (PMID 36550779, 2023). "Additionally, SMAD7 is involved in the TGF-β signaling pathway and can promote tumor growth and metastasis." (PMID 37834191, 2023). "All studied parameters were associated with GC clinical stages except SMAD7 was associated with stage IV only (P = 0.005) and GHRL did not associate with tumor stages (P ˃ 0.05)." (PMID 35449150, 2022). "All studied parameters were associated with GC clinical stages, as their relative median values upregulated with stages (II, III, IV) except SMAD7 was associated with stage IV only and GHRL did not associate with tumor stages." (PMID 35449150, 2022). "Subsequently, we found a different expression of miR-21-5p and Smad7 between tumor tissue and nontumor tissue of clinical samples." (PMID 35518787, 2022). "Circ-SMAD7 restrained ESCC cell proliferation and migration to act as a tumor inhibitor." (PMID 35241028, 2022). "miR-216a-5p has been shown to target SMAD7 and PTEN and enhance tumor progression." (PMID 33511320, 2021). "The effect of MiR-21-3p on tumor phenotypes and YAP1 upregulation could be partly reversed via the restoration of SMAD7 expression in HCC cell lines." (PMID 33763375, 2021). "Subsequently, SMAD7, the target of miR-21-5p, was expressed poorly in tumor tissues (n=33) compared with that of non-tumor lung tissues (n=32)." (PMID 33147570, 2020). "Based on these findings, we hypothesised that cESRP1 inhibits chemoresistance in SCLC by protecting Smad7 and p21(CDKN1A) from downregulation by miR-93-5p, thus inhibiting the tumour-promoting functions of TGF-β signalling." (PMID 31728016, 2020). "In this study, Siglec-15, SMAD7 and ATP5A1 showed the same expression trends in tumors; thus, they may share some pathways that promote tumor aggressiveness." (PMID 32201516, 2020). "Since TGF-β signaling pathway plays contradictory roles in early versus advanced tumor stages, the switch-in role of SMAD7 is not surprising." (PMID 32190221, 2020). "We comprehensively analyzed SMAD7 expression using the XENA database and found that SMAD7 was downregulated in tumor tissues (n=517) compared with non-tumor lung tissue (n=59)." (PMID 33147570, 2020). "A related report concluded that Smad7 prevents radiotherapy-induced oral mucositis but does not prompt tumor growth." (PMID 32117790, 2019). "The function of BAMBI in cancer progression, similar to SMAD7 and BMP7, appears to be context dependent; in colorectal malignancies BAMBI is pro-tumorigenic whereas in the lung and bladder cancer BAMBI exhibits anti-tumor properties." (PMID 29799477, 2018). "Furthermore, disruption of SMAD7 had been reported to play a pivotal role in EMT, which finally contributed to tumor metastasis." (PMID 30419914, 2018). "Pathway analysis suggests that miR-217 could be a potential oncogenic miRNA that negatively regulates the SIRT1, SMAD7, ROBO1, and FOXO3 genes, which are involved in tumor progression by diverse mechanisms." (PMID 30195786, 2018). "Especially in the responder tumor overexpressed transcripts include the growth factors TGFB1 (log 2fc=−2.07) and TGFB1/1 (log 2fc=−3.27) themselves, as well as their direct pathway targets SMAD3 (log 2fc=−2.44) and SMAD7 (log 2fc=−3.86)." (PMID 28594404, 2017). "Here, we show that conditional (TTR-Cre) hepatocyte-specific SMAD7 knockout (KO) mice develop more tumors than wild-type and corresponding SMAD7 transgenic mice 9 months after diethylnitrosamine (DEN) challenge, verifying SMAD7 as a tumor suppressor in HCC." (PMID 28134936, 2017).